TAF1 (TATA-box binding protein associated factor 1)
Diseases named in the same sentence as TAF1 in open-access papers (continued):
Sharing a sentence is not in itself a finding about the gene and the disease.
Intellectual disability (7 papers, 2017 to 2025). "In humans, males with congenital hemizygous mutations in TAF1 (maternally inherited or de novo) show cardinal facial dysmorphologies including microencephaly, with intellectual disability from a young age." (PMID 39323550, 2024). "Congenital hypomorphic mutations in TAF1 in humans result in aberrant development of the brain with corresponding intellectual disability and can also cause congenital heart disease." (PMID 39323550, 2024). "Recently, a study of nine families demonstrated both de novo and maternally inherited single nucleotide changes in TAF1 to be associated with intellectual disability, facial dysmorphology, and neurological manifestations." (PMID 29066808, 2017). "In humans, rare loss of function mutations in TAF1 cause intellectual disability." (PMID 35868859, 2022). "Coding germline variants of TAF1 have been reported to cause intellectual disability (ID)." (PMID 31341187, 2019). "Recent exome sequencing studies have produced compelling evidence that pathogenic variants in TAF1, TAF2, TAF8 and TAF13 are linked to intellectual disability and microcephaly." (PMID 30948355, 2019). "First, variants in TAF1, TAF2, TAF8 and TAF13 have all been linked to intellectual disability and microcephaly." (PMID 30948355, 2019). "A case report of intellectual disability (ID) showed that neuroligin 4 X-linked (NLGN4X, Gene ID: 57502), histone deacetylase 8 (HDAC8, Gene ID: 55869), TATA-box binding protein associated factor 1 (TAF1, Gene ID: 6872), and USP9X genes were associated with XCI escape." (PMID 39891056, 2025). "Common features among affected females with non-XDP TAF1 mutations include intellectual disability and facial abnormalities, as well as congenital heart disease in a similar manner to their male counterparts." (PMID 39323550, 2024).
X-linked intellectual disability (6 papers, 2016 to 2024). An X-linked intellectual deficiency in which not enough information is known, reported or published to indicate whether a gene causes non-syndromic or syndromic presentations. "TAF1 (TATA-Box Binding Protein Associated Factor 1) is associated with X-linked intellectual disabilities and X-linked dystonia." (PMID 35428183, 2022). "In this study, we present a five-generation family affected with X-linked intellectual disability that co-segregated with a TAF1 c.3568C>T, p.(Arg1190Cys) variant." (PMID 31341187, 2019). "Recent sequencing efforts have linked different coding mutations in TAF1 to X-linked intellectual disability." (PMID 26769797, 2016). "Patients with a missense mutation of TAF1 suffer from X-linked intellectual disability." (PMID 36703629, 2022).
neuroblastoma (5 papers, 2015 to 2024). Neuroblastoma (NB) is the most common solid, extracranial childhood tumor. "Another rare variant was identified in the 5′UTR region, located within a binding site of TAF1 transcription factor as reported by the ENCODE database in three different cell lines (lymphoblastoid, human embryonic stem cells and neuroblastoma)." (PMID 25701875, 2015).
schizophrenia (5 papers, 2007 to 2025). A major psychotic disorder characterized by abnormalities in the perception or expression of reality. "Only one study reports that the missense schizophrenia risk variant rs1801311 (located in the 1st exon of NDUFA6 gene) can disrupt the binding of YY1, TAF1, and POLR2A." (PMID 36680208, 2023). "Furthermore, in our analysis, several DE miRNA targets were found to be associated with neuropsychiatric disorders, such as schizophrenia (TTN, SYNPO), depressive disorder (PPARGC1B, TIMELESS), and autism (TAF1, TRIO)." (PMID 31652596, 2019).
acute myeloid leukemia (4 papers, 2019 to 2025). Acute myeloid leukemia (AML) is a group of neoplasms arising from precursor cells committed to the myeloid cell-line differentiation. "Here, we demonstrate that TATA-Box Binding Protein Associated Factor 1 (TAF1) associates with K43 acetylated AE and this association plays a pivotal role in the proliferation of AE-expressing acute myeloid leukemia (AML) cells." (PMID 31664040, 2019). "An inhibitor of TAF-1, BAY 299 is able to induce cell death in acute myeloid leukemia cells, demonstrating its broad therapeutic potential across different cancer types." (PMID 41155227, 2025). "SET-NUP214 fusion gene, also known as TAF-1-CAN and SET-CAN, is observed in acute myeloid leukemia (AML) and T-cell lymphoblastic leukemia (T-ALL)." (PMID 37901324, 2023).
leukemia (4 papers, 2019 to 2025). A malignant (clonal) hematologic disorder, involving hematopoietic stem cells and characterized by the presence of primitive or atypical myeloid or lymphoid cells in the bone marrow and the blood. "Collectively, these data imply that the binding of TAF1 with AE at both promoter and enhancer regions is critical for the expression of a subset of AE target genes, which are implicated in cell cycle and leukemia." (PMID 31664040, 2019). "To further demonstrate that TAF1 loss impairs the growth of leukemia cells in mice, we quantified the number of GFP tagged AE9a+ luciferase+ cells in the peripheral blood 3 weeks after injection using flow cytometry and found far fewer TAF1 KD GFP+ cells." (PMID 31664040, 2019). "There is also genetic evidence for the role of TAF1 in cancer, as mutations in TAF1 were implicated as drivers of clear cell endometrial cancer, and knockdown of TAF1 resulted in decreased proliferation and self-renewal in leukemia cells expressing a splice variant of the AML1-ETO fusion protein." (PMID 40153395, 2025). "To determine whether the endogenous TAF1 protein associates with full-length AE in leukemia cells, we performed reciprocal co-immunoprecipitations using anti- TAF1 and anti- ETO antibodies." (PMID 31664040, 2019). "Consistent, with this finding, TAF1 upregulates cyclin D and cyclin A expression through TAF1 histone acetyltransferase activity and TAF1 has been shown to associate with the leukemia-promoting oncogene AML1-ETO, which promotes proliferation of AML1-ETO-expressing myeloid leukemia cells." (PMID 37746814, 2023). "TAF1 was recently observed to be a key target in leukemia cells possessing the AML1-ETO fusion transcription factor by modulation of protein-protein interactions." (PMID 40153395, 2025). "Single and dual TAF1/FLT3 inhibitors were tested for activity against MOLM13 leukemia cells based on reduction in Cell-titer Glo activity, which corresponds to the number of viable cells, and CellTox Green, which corresponds to the number of dead cells." (PMID 40153395, 2025). "Together, our findings reveal a role of TAF1 in leukemogenesis and identify TAF1 as a potential therapeutic target for AE-expressing leukemia." (PMID 31664040, 2019). "While we now show that targeting TAF1 bromodomains to control AE-related leukemia is a potential therapeutic strategy, further investigation is required to determine the usefulness of TAF1 inhibitors in the treatment of AML." (PMID 31664040, 2019). "TAF1 KD reduces the colony formation of leukemia cells and the numbers of cobblestone area forming cells (CAFCs) indicating that TAF1 is critical for maintaining the self-renewal and frequency of AE9a+ leukemia stem cells." (PMID 31664040, 2019). "Depletion of TAF1 impairs the growth of AE9a+ leukemia cells recapitulating the effects observed on AE-expressing cells." (PMID 31664040, 2019). "Targeting TAF1 impairs the proliferation of AE-expressing leukemia cells and their self-renewal, thereby delaying leukemogenesis." (PMID 31664040, 2019). "We also infected AE9a+ leukemia cells obtained from the secondary transplantation of splenic leukemia cells with either scrambled or TAF1-directed shRNAs before injecting them into recipient mice." (PMID 31664040, 2019). "Together, these data indicate that TAF1 contributes critically to AE9a-induced leukemogenesis, and could serve as a potential target for anti-leukemia therapy." (PMID 31664040, 2019). "However, mice injected with TAF1 KD AE9a+ cells survived substantially longer than mice injected with AE9a+ cells that express wild-type levels of TAF1, implying a pivotal role for TAF1 in leukemia development." (PMID 31664040, 2019). "In MOLM13 leukemia cells, FLT3 inhibitor 3i-1247 was the most potent compound overall, and possessed superb anti-proliferative activity compared to dual FLT3/TAF1 compounds 3i-1246 and 3i-1248." (PMID 40153395, 2025).
leukemia (continued). "In the present study, we confirm that TAF1 is associated with AE in leukemia cells and that knockdown (KD) of TAF1 impairs the self-renewal and promotes the myeloid differentiation and apoptosis of AML cells, thereby impeding leukemia cell growth." (PMID 31664040, 2019). "To evaluate this possibility, we knocked down TAF1 in the non-AE-expressing K562 leukemia cell line and in human CD34+ CB cells." (PMID 31664040, 2019).
prostate carcinoma (4 papers, 2017 to 2025). A carcinoma that arises from epithelial cells of the prostate gland. "TAF1 is implicated in prostate cancer pathogenesis owing to its regulation of the androgen receptor (AR), which represents a sterol receptor that requires multiple components of the transcription machinery to regulate its target genes in the prostate." (PMID 39323550, 2024). "Overexpression or dysregulation of TAF1, driven by genetic and epigenetic changes, was found in NSCLC, where it activates TGFβ1 and is associated with progression of human prostate cancers to the lethal castration-resistant state, is common in various cancers." (PMID 41155227, 2025). "TAF1 was found to increase with the duration of androgen withdrawal in patient samples indicating that it plays a role in castration-resistant prostate cancer." (PMID 39323550, 2024). "The levels of transcription initiation factor TFIID subunit 1 (TAF1), which is part of the basal multiprotein transcription complex TFIID, are linked with prostate cancer progression." (PMID 28486411, 2017).
Ataxia (3 papers, 2018 to 2023). Ataxia refers to impaired coordination of voluntary muscle movement. "In conclusion, our study resolves an undiagnosed case of global developmental delay (motor, cognitive, and speech), hypotonia, possibly ataxia, and cerebellar hypoplasia of unknown origin as we found a new variant in the TAF1 gene, p.Ser1600Gly." (PMID 32714589, 2018). "Here, we used WGS and RNA sequencing (RNA-seq) analysis to identify a novel variant in TAF1 in a patient with global developmental delay (motor, cognitive, and speech), hypotonia, possibly ataxia, and cerebellar hypoplasia of unknown origin." (PMID 32714589, 2018).
endometrial cancer (3 papers, 2022 to 2025). Primary or metastatic malignant neoplasm involving the endometrium (mucous membrane that lines the endometrial cavity). "Notably, TAF1 mutations occur in over 20% of uterine corpus endometrial carcinoma (UCEC) samples, a frequency that correlates with decreased progression-free survival in this cohort, suggesting TAF1 as a candidate biomarker and potential therapeutic target in endometrial cancer." (PMID 40591126, 2025).
autism spectrum disorder (2 papers, 2021 to 2024). A spectrum of developmental disorders that includes autism, and Asperger syndrome. "Recently, interest in the role of T-type calcium channels in the brain has increased because of their importance in neurodevelopmental disorders such as autism spectrum disorder, neural tube defects, and TATA-box binding protein associated factor 1 (TAF1) intellectual disability (ID) syndrome." (PMID 33359140, 2021).
breast carcinoma (2 papers, 2022 to 2025). "The large majority (10/13) of these genes were reported to play a role in the regulation of estrogen and/or progesterone response in human breast cancer (NCOA7:; NCOA3:; USP22:; MED24:; CCAR1:; CRY2:; STAT5B:; PAGR1:; TAF1:; PHB2:)." (PMID 35996163, 2022).
colorectal cancer (2 papers, 2023 to 2025). A primary or metastatic malignant neoplasm that affects the colon or rectum. "As indicated in Oh’s study, the TAF1 frameshift mutation reduces cell death and contributes to the survival of gastric and colorectal cancer cells." (PMID 38045002, 2023).
esophageal cancer (2 papers, 2022 to 2024). A primary or metastatic malignant neoplasm involving the esophagus. "Research has shown that reducing the levels of the long noncoding RNA DDX11-AS1 in esophageal cancer cells can lessen their resistance to paclitaxel by inhibiting TAF1/TOP2A." (PMID 39183398, 2024). "A recent study found that resistance of esophageal cancer cells to paclitaxel can be reduced by the knockdown of the long non-coding RNA DDX11-AS1 through TAF1/TOP2A inhibition." (PMID 35444699, 2022).
female sterility (2 papers, 2010 to 2013). "The Taf1 gene, which is involved in female sterility, might correspond to QTL2 found in this study." (PMID 23950867, 2013). "Moreover, from among 23 loss-of-function mutations found in a genetic screen of Taf1, three were identified as causing female sterility without affecting the fertility of males." (PMID 21144061, 2010).
glioblastoma (2 papers, 2014 to 2022). The most malignant astrocytic tumor (WHO grade IV).
Huntington disease (2 papers, 2024 to 2026). Huntington disease (HD) is a rare neurodegenerative disorder of the central nervous system characterized by unwanted choreatic movements, behavioral and psychiatric disturbances and dementia. "XDP brains have striatal atrophy and patients manifest late-onset motor impairment similar to that in Huntington’s disease (HD), in which reduced TAF1 protein expression has been reported." (PMID 39323550, 2024). "In Huntington’s disease (HD), alternative splicing alteration emerged as a molecular mechanism in view of individually reported mis-splicing events in neurodegeneration-linked genes such as HTT itself, MAPT and TAF1." (PMID 41928095, 2026).
intellectual disability syndrome (2 papers, 2018 to 2023). "Taken together, our data suggest that this novel variant in TAF1 plays a key role in the development of a recently described X-linked syndrome, TAF1 intellectual disability syndrome, and further extends our knowledge of a potential link between TAF1 deficiency and defects in neuronal cell function." (PMID 32714589, 2018). "Loss of TAF1 in rats alters the morphology and function of the cerebellum and cerebral cortex, and leads to hypoplasia and loss of Purkinje cells, with behavioral abnormalities paralleling that seen in TAF1/MRSX33 intellectual disability syndrome." (PMID 37746814, 2023).
uterine serous carcinoma (2 papers, 2019 to 2023). "In uterine cancers, TAF1 has been nominated as a candidate driver gene in uterine serous carcinoma, and somatic mutations of TAF1 have been found in some ECCCs." (PMID 38045002, 2023).
X-linked syndromic mental retardation 33 (2 papers, 2017 to 2022). "Hemizygous missense and splice-site TAF1 variants, and duplication involving TAF1, are associated with X-linked syndromic mental retardation 33 (OMIM 300966), which is a severe neurodevelopmental disorder and has dystonic features." (PMID 28672841, 2017).
adult T-cell acute lymphoblastic leukemia (1 paper, 2024). "The SET-NUP214 (TAF1/CAN) fusion gene has shown a strong association with chemotherapy resistance in adult T-cell acute lymphoblastic leukemia." (PMID 39338204, 2024).
brain malformations (1 paper, 2019). "Quantification of tectum size was performed as a proxy for brain malformations previously reported in patients with TAF1 variants." (PMID 31341187, 2019).
colitis (1 paper, 2025). Inflammation of the colon. "In contrast, silencing TAF1 expression in IL-9-stimulated fibroblasts reduced the expression of Col1a1, Col3a1, collagen I, and collagen III, suggesting that IL-9 interacts with ETV5 and subsequently regulates TAF1, thereby contributing to the production of colitis-associated inflammatory factors." (PMID 40771819, 2025).
congenital heart disease (1 paper, 2024). A heart disease that is present at birth. "Furthermore, missense variants in TAF1 cause congenital heart disease, indicating that TAF1 function is required for cardiac development." (PMID 39323550, 2024). "Additionally, TAF1 may have a specific role in cardiac function, where loss of function causes congenital heart disease, owing to the epigenetic modulatory role of its double BrD in regulating foetal myosins." (PMID 39323550, 2024).
COVID-19 (1 paper, 2021). A disease caused by infection with severe acute respiratory syndrome coronavirus 2. "NKTR and its PPI partners transcription initiation factor TFIID subunit 1 (TAF1), 40S ribosomal protein S14 (RPS14), and arrestin beta 2 (ARRB2) are differentially expressed in the PBMCs of COVID-19 patients." (PMID 34108016, 2021).
heart failure (1 paper, 2023). Inability of the heart to pump blood at an adequate rate to meet tissue metabolic requirements. "Brightfield and fluorescent microscopy revealed classical signs of heart failure in taf5 and taf1 mutant (loss of function, null alleles) as measured by reduced ejection fraction, dimensional cardiomyocyte strain, and pericardial edema." (PMID 37746814, 2023). "Importantly, these metabolic derangements were absent in N2:TTNa mutants with akinetic hearts indicating that metabolic impairments found in taf1 and taf5 embryos were not secondary to heart failure." (PMID 37746814, 2023).
hepatocellular carcinoma (1 paper, 2023). A malignant tumor that arises from hepatocytes. "Some data suggest that TAF1 may contribute to the progression of hepatocellular carcinoma (HCC) and is significantly associated with OS in patients with HCC, but other studies have shown that inactivation of TAF1 may be involved in tumorigenesis." (PMID 38045002, 2023).
melanoma (1 paper, 2016). A malignant, usually aggressive tumor composed of atypical, neoplastic melanocytes. "In melanomas, TAFH RNAi induced the differential expression of TBP, TAF1, TAF2, TAF6, TAF10, and TAF12 ASVs." (PMID 27499390, 2016).
myeloid leukemia (1 paper, 2023). A clonal proliferation of myeloid cells and their precursors in the bone marrow, peripheral blood, and spleen. "Furthermore, TAF1 is required for leukemic cell self-renewal, and its reduction promotes the differentiation and apoptosis of AML1-ETO+ myeloid leukemia cells." (PMID 37746814, 2023).
myeloma (1 paper, 2025). "According to the research results of cell type-specific regulatory activity, the most activated TFs in these myeloma cell subgroups included ETV7(C0 GNB2L1+ NK cells), TAF1(C1 RACK1+ NK cells), POU2F2(C2 HNRNPH1+ NK cells), and RUNX2(C3 ATP5E+ NK cells)." (PMID 40454289, 2025).
thymoma (1 paper, 2015). A neoplasm arising from the epithelial cells of the thymus. "The “TF-lncRNA” core network map for MG patients without thymoma versus MG patients with thymoma indicated that TF TAF1 modulated the expression of 8 lncRNAs." (PMID 25889429, 2015).
thyroid carcinoma (1 paper, 2020). "In thyroid carcinoma, LINC00511 could interact with TAF1 to upregulate JAK2, which then activated STAT3 signaling pathways to maintain the resistance to radiotherapy of malignant cells." (PMID 32713253, 2020).
uterine corpus endometrial carcinoma (1 paper, 2025). A endometrial carcinoma (disease) that involves the body of uterus. "Gene expression analysis showed limited overall significance, but TAF1 was notably upregulated in uterine corpus endometrial carcinoma (UCEC), while RNF115 and RNF141 were downregulated in the same cancer type." (PMID 40591126, 2025).